G6PC2 (glucose-6-phosphatase catalytic subunit 2)
Description:
May hydrolyze glucose-6-phosphate to glucose in the endoplasmic reticulum. May be responsible for glucose production through glycogenolysis and gluconeogenesis (By similarity).
Synonyms: IGRP
Tractability: Antibody: UniProt predicts a signal peptide or a membrane-spanning region.
Gene: Protein-coding gene on chromosome 2 (168,901,291 to 168,910,000, forward strand). Ensembl gene ENSG00000152254.
Subcellular location: Endoplasmic reticulum membrane
Pathways (Reactome):
Metabolism: Gluconeogenesis
Gene Ontology:
Molecular function: glucose-6-phosphatase activity
Biological process: glucose homeostasis; regulation of insulin secretion; gluconeogenesis; glucose 6-phosphate metabolic process
Cellular component: endoplasmic reticulum membrane; membrane; endoplasmic reticulum
Genetic constraint (gnomAD): Loss-of-function variants: 12 observed, 11.32 expected, observed/expected ratio (o/e) 1.06, 90% interval 0.68 to 1.68. The upper end of that interval is the gene's LOEUF score, 1.68, which puts it in group 6 of 6, group 1 being the genes least tolerant of losing a copy. Missense variants: 211 observed, 213.44 expected, observed/expected ratio (o/e) 0.99, 90% interval 0.88 to 1.11. Synonymous variants: 87 observed, 88.51 expected, observed/expected ratio (o/e) 0.98, 90% interval 0.83 to 1.17.
Homologues: Orthologues: chimpanzee G6PC2 (99% identical), macaque G6PC2 (93% identical), rabbit G6PC2 (91% identical), dog G6PC2 (89% identical), guinea pig G6PC2 (89% identical), pig G6PC2 (88% identical), mouse G6pc2 (84% identical), rat AABR07052465.1 (34% identical), Drosophila melanogaster G6P (23% identical). Paralogues in human: G6PC1 (51% identical), G6PC3 (34% identical).
Diseases named in the same sentence as G6PC2 in open-access papers:
G6PC2 is named in the same sentence as 26 diseases in open-access papers, as found by Europe PMC text mining. Sharing a sentence is not in itself a finding about the gene and the disease. The quoted sentences say what the papers report.
diabetes (27 papers, 2008 to 2025). "The evidence that the variants GCK rs1799884, GCKR rs780094, MTNR1B rs10830963 and G6PC2 rs560887, which are related to fasting plasma glucose levels, increase the risk of type 2 diabetes mellitus (T2DM) is contradictory." (PMID 23840762, 2013). "While associations at the GCK, SLC30A8 and G6PC2 loci confirm or extend previous work done on the genetic basis of diabetes or fasting glucose, our replicated findings at HK1 are novel." (PMID 19096518, 2008). "STZ treatment also suppressed expression of a wide range of genes linked with key β-cell functions or diabetes development, such as G6pc2, Slc2a2 (Glut2), Slc30a8, Neurod1, Ucn3, Gad1, Isl1, Foxa2, Vdr, Pdx1, Fkbp1b and Abcc8, suggesting global β-cell defects in STZ-treated islets." (PMID 23828045, 2013). "G6PC2 encodes the islet-specific glucose-6-phosphatase catalytic subunit-related protein (IGRP) and is crucial for blood glucose regulation and diabetes pathophysiology." (PMID 41450548, 2025). "Specifically in β-cells, TG-induced stress resulted in increased expression of ARID5B (part of demethylase complex), MAP1LC3A (Mitophagy), and CLIC1 (chloride channel) expression and decreased G6PC2 and HADH, which have been associated with diabetes." (PMID 38956087, 2024). "For example, G6pc2, Pfkfb2, Ogdh1 and Cox6a2 were significantly affected by 4 weeks of diabetes but were unchanged by 24 h of hyperglycaemia." (PMID 27882918, 2016). "Interestingly, at least 12 genes including SLC2A2, G6PC2, SLC30A8, PCSK1 and RAPGEF4, also overlap with previously implicated genes from genome wide association studies (GWAS) for type 2 diabetes mellitus and blood glucose loci." (PMID 31682591, 2020). "While associations with the GCK, SLC30A8, and G6PC2 genes have previously been identified in genetic studies of diabetes and blood glucose concentration, the findings at HK1 are novel." (PMID 19096518, 2008).
type 2 diabetes (13 papers, 2010 to 2025). "Among the four genes studied, we found only GCKR rs780094 and G6PC2 rs16856187 affected type 2 diabetes risk in our samples." (PMID 20668700, 2010). "G6PC2 is associated with increased susceptibility to type 2 diabetes." (PMID 39786569, 2025). "G6PC2 modulates fasting blood glucose level and susceptibility to type 2 diabetes." (PMID 35726320, 2022). "In the GLACIER cohort, eleven loci (including the known type 2 diabetes genes TCF7L2 and SLC30A8) were nominally associated with IFG cross-sectionally, and MTNR1B and G6PC2 were also associated with development of IFG in longitudinal analyses." (PMID 22984506, 2012). "In conclusion, we showed that GCK, G6PC2 and MTNR1B variants modulated fasting glucose levels while G6PC2 and GCKR variants were associated with type 2 diabetes in the Shanghai Chinese." (PMID 20668700, 2010). "We showed that SNPs from GCK, G6PC2 and MTNR1B modulated the fasting glucose levels in the normoglycaemic population while SNPs from G6PC2 and GCKR was associated with type 2 diabetes." (PMID 20668700, 2010). "Because elevated FBG is associated with increased risk for Type 2 diabetes (T2D), cardiovascular associated mortality (CAM), adverse pregnancy outcomes, heart disease, brain atrophy, and several types of cancer, G6PC2 inhibitors that lower FBG could have multiple therapeutic benefits." (PMID 38095063, 2024). "Module 84 contained three effector genes from the Type 2 Diabetes Knowledge Portal—ABCC8, SLC30A8, and G6PC2—and module 103 included two effector genes: PAX6 and STARD10." (PMID 37333221, 2023). "Of the 132 type 2 diabetes Knowledge Portal effector genes, we identified 18 (14%) as candidate effector genes for at least one phenotype, including ABCC8, KCNJ11, NKX2–2, G6PC2, PAM, HNF4A, SLC30A8, RFX6, PCSK1, and GLIS3." (PMID 37333221, 2023). "Previous studies identified melatonin receptor 1B (MTNR1B), islet-specific glucose 6 phosphatase catalytic subunit-related protein (G6PC2), glucokinase (GCK) and glucokinase regulatory protein (GCKR) as candidate genes for type 2 diabetes (T2D) acting through elevated fasting plasma glucose (FPG)." (PMID 20628598, 2010).
insulinoma (3 papers, 2020 to 2022). "In contrast, glucose cycling studies in INS1-832/13 cells, a rat insulinoma cell line, showed negligible glucose cycling (≤3%) and net release of glucose (∼1 nmol/106 cells/hr), further validating that G6pc2 is a pseudogene in rats." (PMID 35176280, 2022).
Obesity (3 papers, 2015 to 2022). Accumulation of substantial excess body fat. "More broadly, these data suggest that G6PC2 could be a potential target for enhancing insulin secretion as well as lowering FBG in individuals with prediabetes, type 2 diabetes (T2D) and obesity." (PMID 35176280, 2022). "Overall, our findings implicate G6PC2 as a potential therapeutic target for enhancing insulin secretion and lowering FBG, which could benefit individuals with prediabetes, T2D, and obesity." (PMID 35176280, 2022).
breast carcinoma (2 papers, 2017 to 2019). "In phenotype-specific analysis, genetically elevated FG was associated with reduced risk for breast cancer (main contributor of this MR-effect estimate: G6PC2 rs13431652; HR = 0.59, 95% CI: 0.35–0.99)." (PMID 31246991, 2019).
Hypoglycemia (2 papers, 2022 to 2024). A decreased concentration of glucose in the blood. "Isolated islets from G6PC2−/− mice exhibit a left shift in GSIS, such that under fasting conditions, insulin levels are the same as wild-type mice, inferring G6PC2’s potential role in protecting against hypoglycemia under stressed conditions." (PMID 38731997, 2024). "In our model, G6PC2 was downregulated in response to hypoglycemia and could contribute to a potentially altered GSIS response in our fetuses." (PMID 38731997, 2024).
Insulin resistance (2 papers, 2021 to 2025). Increased resistance towards insulin, that is, diminished effectiveness of insulin in reducing blood glucose levels. "Additionally, a recent study has revealed that circRNA hsa_circ_0046060 inhibits miR-338-3p expression, leading to upregulation of G6PC2 and exacerbation of insulin resistance." (PMID 40652291, 2025).
acute pancreatitis (1 paper, 2022). An acute inflammatory process that leads to necrosis of the pancreatic parenchyma. "Similarly, we showed that the G6PC2 rs560887 “A” allele, which reduces G6PC2 expression, is associated not only with reduced blood glucose, but also with increased taurine levels and increased risk for acute pancreatitis." (PMID 34954144, 2022).
glioma (1 paper, 2021). A benign or malignant brain and spinal cord tumor that arises from glial cells (astrocytes, oligodendrocytes, ependymal cells). "In addition, there is no research on B4GALT7, CHST12, G6PC2 and TPBG in glioma." (PMID 33553434, 2021).
glycogen storage disease (1 paper, 2016). "Supporting this hypothesis is the observation that of the 56 AAs in human G6PC1 mutation of which gives rise to glycogen storage disease (GSD) type 1a, 51 are conserved or represent conserved changes in human G6PC2." (PMID 27611587, 2016).
hyperinsulinism (1 paper, 2021). Abnormally high levels of insulin in the blood. "For example, glucose-6-phosphatase 2 (G6PC2) harbors genetic variants associated with reduced fasting glycemia, while the abnormal beta cell expression of “disallowed gene” hexokinase I (HK1) has been linked to congenital hyperinsulinism." (PMID 33828531, 2021).
pancreatic cancers (1 paper, 2017). "GCK opposing G6PC2 encodes for glucokinsase, and mutation of this gene is related to DM and glucose metabolism; further, the GCK variant is associated with prostatic and pancreatic cancers." (PMID 28446149, 2017).
cancer (1 paper, 2017). A tumor composed of atypical neoplastic, often pleomorphic cells that invade other tissues. "Expression of the G6PC2 gene (glycolytic inhibitor) is elevated in cancer cells and related to a decreased survival rate in cancer patients, suggesting its role in glucose metabolism and cell cycle control in cancer cells." (PMID 28446149, 2017).
infection (1 paper, 2020). The state of being infected such as from the introduction of a foreign agent such as serum, vaccine, antigenic substance or organism. "Transcripts for canonical β-cell markers including PDX1, FOXA2, G6PC2, and PAX6 were present at low levels and also decreased following infection but were not amongst the top 1000 differentially expressed transcripts." (PMID 32093375, 2020).
metabolic disorders (1 paper, 2017). "We also perform an association study to assess the role of G6PC2 variants in T2D susceptibility in a population with high incidence of metabolic disorders." (PMID 28173748, 2017). "We thus investigated a possible role for G6PC2 variants in modulating the susceptibility to T2D in subjects from Saudi Arabia, a region with a high prevalence of metabolic disorders, including T2D." (PMID 28173748, 2017).
G6PC2 also shares sentences with these, for which no sentence is quoted: type 1 diabetes (10 papers); Autoimmunity (6); hyperglycaemia (3); autoimmune disease (2); co-infection (1); influenza (1); maturity-onset diabetes of the young (1); melanoma (1); prediabetes (1); tetanus (1); tumor (1).